INS (insulin)
Diseases named in the same sentence as INS in open-access papers (continued):
Sharing a sentence is not in itself a finding about the gene and the disease.
Insulin resistance (continued). "Regarding metabolic parameters, basal glucose levels did not significantly differ between groups, while insulin levels and the degree of insulin resistance assessed by HOMA-IR index were higher in OSA patients than in those without OSA, but these differences were not statistically significant." (PMID 32850919, 2020). "Of note, the insulin secretion evaluated by FCP and 2-h PCP and insulin resistance quantified by HOMA2-IR were intermediate between type 1 diabetics and non-ketotic type 2 diabetics in our research, which may occur due to remission duration after initial metabolic disturbance." (PMID 31049079, 2019). "We did not assess serum concentration of insulin and insulin resistance in these patients; these could have helped to confirm hyperinsulinaemia as a risk factor for AsVD among CAPD patients." (PMID 31666030, 2019). "In addition, patients with a classical T1D can develop insulin-resistance despite the lack of endogenous insulin production, often referred to as double-diabetes." (PMID 30837889, 2019). "However, administration of the neurotrophic factor did not significantly change the peripheral insulin resistance, as shown by the plasma levels of insulin, glycemia, and HOMA index, nor did it rescue the hyperphosphorylation of ovarian IRS1Ser612." (PMID 31641124, 2019). "With the onset of inflammation and insulin resistance in WAT, there is an increase of free fatty acids (FFA) release, which can penetrate into the circulation and are transported by other organs, such as the liver, skeletal muscles, and brain, increasing the insulin resistance in these organs." (PMID 31683535, 2019). "Interestingly, evidence in animals and humans indicates that the PI3K-dependent pathway is selectively attenuated in insulin resistance without any effect on Raf/MAPK insulin signaling." (PMID 31382355, 2019). "The STZ-treated mice in our study might also suffer serious insulin resistance, and the increasing insulin levels in the peptide II-treated group are not enough to improve the HbA1c levels." (PMID 30646613, 2019). "However, recent studies have shown that taking dutasteride can increase body fat and decrease insulin sensitivity, whereas finasteride has no such effect and can improve insulin resistance." (PMID 31001337, 2019). "Since a body of evidence demonstrated the involvement of PRX3 in insulin secretion, insulin sensitivity, and glucose metabolism, the present study was conducted to investigate the role of PRX3 in the pathogenesis of polycystic ovarian syndrome (PCOS) featured in insulin resistance." (PMID 30871530, 2019). "Systemic (whole body) insulin resistance has been defined by the “homeostasis model assessment for insulin resistance (HOMA-IR: normal; <1.6, insulin resistance; >2.5)”, which is calculated as follows: fasting plasma glucose (mmol/L) × fasting serum insulin (IU/L)/405." (PMID 31330848, 2019). "Previous studies suggested an essential role of insulin resistance in the hyperphosphorylation of tau, but whether insulin resistance contributes to iron-induced tauopathy has not been determined." (PMID 31275224, 2019). "Although hyperglycemia represents the more plausible primary driver of mitochondrial dysfunction, the potential involvement of insulin resistance should not be overlooked in consideration of the role of insulin in inducing mitochondrial biogenesis by promoting the SIRT1/PGC1α pathway." (PMID 31787891, 2019). "Moreover, although increasing HOMA-IR reflects enhanced insulin resistance, we believe that HOMA-IR is indicative only within certain limits and HOMA-IR beyond the normal range could be explained as the abnormality of insulin metabolism." (PMID 31847151, 2019). "This suggest the onset of insulin resistance in HFF rats at the level of skeletal muscle since, following a meal, approximately one third of ingested glucose is taken up by the liver and the rest by peripheral tissues, primarily skeletal muscle via an insulin dependent mechanism." (PMID 31689911, 2019).
Insulin resistance (continued). "Consequently, high homeostasis model assessment insulin resistance (HOMA-IR), β-cell function (HOMA-β), and the reduced liver insulin sensitivity index (LISI) values (markers of insulin resistance) displayed by MSG rats were all fully repealed when treated with NAC." (PMID 30906502, 2019). "We hypothesized that AS160-KO rats compared to WT littermates would be characterized by whole body insulin resistance and glucose intolerance concomitant with lower GLUT4 protein abundance and glucose uptake in insulin-stimulated skeletal muscles, WAT, and the heart." (PMID 31034517, 2019). "When insulin sensitivity declines, insulin secretion must increase to maintain glucose tolerance and finally when β-cells are no longer able to secrete sufficient insulin to overcome insulin resistance, IGT ensues progressing to T2D." (PMID 31555201, 2019). "Interestingly, in the obese group, T. cruzi infection intensified insulin resistance, practically without altering the glycaemic level after the application of insulin." (PMID 31827186, 2019). "Although NAFLD may promote hepatic insulin resistance, there are also other examples of diet-induced moderate liver fat accumulation without concomitant impairment of insulin sensitivity." (PMID 31369090, 2019). "Measurements of insulin were missing in three patients, one unaffected relative and three healthy individuals, consequently these seven participants were only included in analyses of metS but not of insulin resistance." (PMID 30937579, 2019). "Impaired insulin signal transduction may be explained by a principal molecular mechanism, the serine phosphorylation of insulin receptor substrate 1 (IRS-1), which mediates insulin resistance through inhibitory effects on glucose transporter 4 (GLUT4)." (PMID 31485456, 2019). "Thus, macrophages lacking insulin signaling exhibit reduced responses to pathogens and altered metabolism, suggesting that insulin resistance is a state of trained immunity." (PMID 31244863, 2019). "Being neither insulin insensitivity nor insulin resistance, the current model with 8-week HFD might only induce beta cell proliferation as reported." (PMID 31371780, 2019). "Interestingly, our data indicate that NGF may counteract the detrimental effects of brain insulin resistance by acting on the IRS1 stimulation, the early, main and common effector of insulin and IGF1 receptors signalings." (PMID 29736736, 2019). "Nevertheless, this apparently contradictory evidence should be examined in light of previous information showing that healthy young adults with no insulin resistance have the ability to increase insulin secretion and thus effectively decrease the excess of blood glucose." (PMID 31183389, 2019). "Although increased leptin, insulin and C-peptide levels may be involved in insulin resistance, increased adiposity and macrosomia, they were not significantly deviated from published data from other populations." (PMID 31975995, 2019). "As a negative effector of the insulin signaling pathway, GSK3β is involved in insulin resistance." (PMID 31293498, 2019). "The initial findings of our study demonstrated that a decrease in the expression of SAA1 could improve glucose tolerance in mice on HFD; moreover, there exists a positive correlation between SAA1 and insulin resistance and that the silencing of SAA1 results in an increase in insulin sensitivity." (PMID 31060494, 2019). "Also, AHG improved insulin tolerance, glucose tolerance and alleviated serum insulin content in HFD group mice, suggesting that AHG improved insulin sensitivity induced by HFD, these provided insight into the anti-insulin resistance actions of AHG." (PMID 31861309, 2019). "Moreover, GDM women without increases in insulin resistance also had impaired insulin secretion and tended to be leaner prior to pregnancy compared to GDM women with high insulin resistance (HIR group)." (PMID 31275653, 2019).
Insulin resistance (continued). "However, it aggravated the HCV-induced insulin resistance by interfering with insulin signal molecules and did not directly modify HCV infection in the HCV-infected cells." (PMID 30984779, 2019). "LCD may increase insulin sensitivity in PCOS patients by restoring the balance of inositol, thereby improving insulin resistance, decreasing the level of androgen, and restoring the regularity of the menstrual cycle and quality of oocytes in patients with PCOS." (PMID 31885557, 2019). "Drugs based on mechanisms of action that directly stimulate uptake of glucose by skeletal muscle tissues, independent of endogenous and exogenous insulin, are thus needed for individuals who have developed insulin resistance or are experiencing undesired side effects with current treatments." (PMID 31069401, 2019). "Insulin sensitivity, as determined by the homeostasis model assessment for insulin resistance (HOMA-IR) or an oral glucose tolerance test, is not reduced in TM6SF2 gene variant carriers, and serum triglyceride and LDL cholesterol concentrations are lower compared with non-carriers." (PMID 31447675, 2019). "The influence and role of bioactive lipids for insulin resistance in humans are yet to be fully clarified, whereas in rodents and cell studies, the bioactive lipids ceramide and diacylglycerol (DAG) have been shown to induce adverse effects on insulin signaling in skeletal muscle." (PMID 30871020, 2019). "It was Gerald Reaven who first proposed the name “insulin resistance syndrome” to this risk factor clustering as he noticed and later demonstrated that adults with the metabolic syndrome tend to have lower insulin sensitivity (in other words—insulin resistance) compared to those who do not." (PMID 31474943, 2019). "Moreover, ANGPTL-4 presented a negative correlation with BMI, waist circumference, weight, insulin, homeostasis model assessment of insulin resistance index (HOMA index), triglycerides, and leptin, and a positive correlation with FFA and vitamin-D." (PMID 31207920, 2019). "Consequently, GCE-treated mice consistently showed decreased insulin resistance and improved insulin sensitivity, with no changes in β-cell function, as assessed by the HOMA and QUICKI indices." (PMID 30818779, 2019). "The Spirulina maxima 250 group showed reduced glucose and insulin levels (insulin levels also in the Spirulina maxima 125 group), and all the tested doses of the microalga diminished HOMA-IR values, reflecting the amelioration in insulin resistance induced by the HFD." (PMID 31861663, 2019). "Furthermore, in several rodent models of insulin resistance and type 2 diabetes, intimal hyperplasia after vascular injury is more severe than the non-diabetic or insulin-sensitive controls." (PMID 31562314, 2019). "In the insulin resistant state, patients develop compensatory hyperinsulinemia but insulin’s vascular responses through the PI3-kinase/Akt/eNOS pathway are attenuated while its actions via the MAPK pathway remain intact or even enhanced (i.e., a pathway selective insulin resistance)." (PMID 30699907, 2019). "In the present model the apparent Corkey paradox is replicated (glycemia not immediately rising upon worsening of insulin resistance), due to the controlling effects of increased insulin secretion up to the point where relative endocrine pancreatic insufficiency develops." (PMID 31600232, 2019). "However, there was no compensatory increase in insulin levels, which is normally the primary reaction upon developing insulin resistance." (PMID 31487806, 2019). "Giving insulin with strict monitoring of the blood glucose level might conquer the barrier of insulin resistance and benefit patient metabolism without significant side effects." (PMID 31353827, 2019).
Insulin resistance (continued). "Several factors contribute to an increase in plasma BCAAs during insulin resistance, such as increasing BCAA production from gut microbiota, decreasing BCAA catabolism in adipose tissues, and decreasing liver catabolism by decreased hypothalamic insulin signaling." (PMID 31248127, 2019). "This trial demonstrate that daily supplementation with 1500 mg curcumin for 10 weeks could decrease fasting blood glucose in patients with type 2 diabetes, but no significant changes observed in serum insulin level, insulin resistance and HBA1c." (PMID 31149032, 2019). "Furthermore, HFD-induced insulin resistance and impaired glucose tolerance, as determined by the glucose tolerance test (GTT) and insulin tolerance test (ITT), respectively, were significantly attenuated in SCFA-fed mice as compared to those in cellulose-fed and control mice." (PMID 31719611, 2019). "This is consistent with our previous observation that aromatase inhibition is likely to mediate increased insulin resistance through reduced peripheral glucose disposal in skeletal muscle (captured by the dynamic insulin sensitivity index but not the static HOMA-IR)." (PMID 30920624, 2019). "Insulin treatment in GDM could result in restoration of the expression and activity of insulin and adenosine receptors and the l-arginine–NO signaling pathway as well as promote placental fatty acid transfer and overcome placental insulin resistance." (PMID 30873116, 2019). "Still, as both insulin serum levels and HOMA-IR were significantly higher in MUH children when compared to MH children (+~33% and +~37%, respectively; p < 0.05 for both), it can be assumed that at least some of the MUH children suffered from early stages of insulin resistance." (PMID 30889844, 2019). "In this study, a direct correlation between serum vaspin level and HOMA-IR and insulin levels, which are indicators of insulin resistance, could not be determined in the CKD group." (PMID 30881429, 2019). "To date, however, the molecular mechanism(s) underlying the beneficial effects of oleacein on adipogenesis and peripheral insulin resistance have not been explored intensely, so that its role on insulin sensitivity and its implications for metabolic functions need to be addressed." (PMID 31394876, 2019). "Insulin resistance is a condition in which an organism fails to respond to endogenous insulin." (PMID 30781350, 2019). "Correspondingly, EGFR inhibition could substantially improve insulin sensitivity by reducing inflammation in insulin target tissue in obese mice, where EGFR inhibition enhances IRS-1 signaling, providing a potential therapeutic target for insulin resistance." (PMID 31815004, 2019). "However, unlike pubertal mice, treatment of adult female mice resulted in modest weight gain and abdominal adiposity, minimal elevation in fasting blood glucose and insulin levels, and no detectable insulin resistance." (PMID 30871463, 2019). "Therefore, these genes with similar changes between insulin treatment or non-insulin treatment LADA patients may play important roles in insulin resistance." (PMID 31950067, 2019). "However, the acute response of Nur77 and NOR1 gene and protein expression in response to insulin has not been characterized in the context of obesity, insulin resistance or T2DM." (PMID 30912283, 2019). "Therefore, an agent that possesses insulin sensitizing effect without stimulating adipogenesis can be advantageous in the management of insulin resistance." (PMID 31226166, 2019). "A harmful cycle arises when FFA are not properly regulated by insulin contributing to the development of insulin resistance, a key indicator for T2DM, since prolonged insulin resistance may lead to hyperglycemia." (PMID 31499737, 2019).
Insulin resistance (continued). "Failure on effective insulin clearance dramatically increases insulin action in the short term, whereas in the long term it leads to decreased amounts of INSR on the plasma membrane and contributes to the progression of insulin resistance and further into T2DM." (PMID 31658625, 2019). "There was no clear effect of supplementation on glucose handling (Homeostatic Model Assessment of Insulin Resistance (HOMA-IR) and Gutt indices), although the Matsuda index decreased significantly in the MC group post-supplementation, reflecting an increase in serum insulin concentration." (PMID 31085979, 2019). "This could suggest that once brain insulin resistance has developed, insulin treatment may not be sufficient to overcome resistance at the cellular level." (PMID 31160730, 2019). "Puzzlingly, rapamycin can induce insulin sensitivity, but may also induce insulin resistance or glucose intolerance without insulin resistance." (PMID 31406105, 2019). "Third, our MR study assessing the role of endogenous insulin and insulin resistance might not be applicable to the exogenous use of insulin." (PMID 31508506, 2019). "Two main reasons may explain the link between T2DM and hyperlipidemia: the metabolic factors such as insulin resistance and abdominal obesity and the lack of insulin and insulin resistance leading to defects in the removal of LDL-C and TG." (PMID 30777111, 2019). "Such alterations may exaggerate insulin response in the short term due to INSR retention on the plasma membrane, but may lead to a long-term decrease in INSR membrane expression due to reduced INSR recruitment and development of insulin resistance." (PMID 31658625, 2019). "We hypothesize that when insulin ineffectively regulates FFA, then higher FFA may reduce glucose transport, leading to a harmful cycle promoting hyperglycemia and thus contributing to the development of insulin resistance in the long-term." (PMID 31499737, 2019). "In addition, we measured insulin sensitivity in mice by GTT and insulin resistance test." (PMID 31060494, 2019). "In other words, sucralose ingestion may stimulate insulin secretion and, in this way, reduce glucose levels in healthy young adults but not morbidly obese subjects that show higher levels of insulin resistance and thus glucose intolerance." (PMID 31183389, 2019). "Insulin resistance/sensitivity was determined by the quantitative insulin sensitivity check index (QUICKI), homeostasis model assessment-insulin resistance (HOMA-IR), insulin-to-glucose ratio, McAuley index, revised McAuley index, fasting insulin resistance index (FIRI), and Bennett’s index." (PMID 30866603, 2019). "However, IRS1 mSer307 knock-in mice display insulin resistance rather than increased insulin sensitivity, suggesting that IRS1 mSer307 is a positive regulatory site and is essential for normal insulin signaling." (PMID 31426549, 2019). "However, no insulin tolerance tests were performed to confirm that these findings are due to insulin resistance." (PMID 29847581, 2018). "Insulin resistance is a state where body secretes insulin but does not use it properly." (PMID 30356972, 2018). "Consequently, unrestrained WAT lipolysis results in increased fatty acid release, leading to lipotoxicity and insulin resistance, while impaired lipogenesis in WAT decreases the synthesis of insulin-sensitizing fatty acid species, which also leads to insulin resistance." (PMID 30274245, 2018). "In liver, contrary to ER stress response, iNOS alone was not sufficient to account for the insulin resistance, as iNOS blockade did not improve glucose metabolism, whereas ER stress pharmacological blockade restored glucose tolerance and insulin sensitivity of the liver." (PMID 29921793, 2018). "Notably, upon insulin resistance, while insulin fails to exert its effects on glucose homeostasis, insulin still is able to enhance lipogenesis." (PMID 30310815, 2018).